PHACTR2-AS1 (PHACTR2 antisense RNA 1)
Synonyms: NR027113; lncIHS
Gene: Long non-coding RNA gene on chromosome 6 (143,554,325 to 143,562,031, reverse strand). Ensembl gene ENSG00000235740.
Diseases named in the same sentence as PHACTR2-AS1 in open-access papers:
PHACTR2-AS1 is named in the same sentence as 1 disease in open-access papers, as found by Europe PMC text mining. Sharing a sentence is not in itself a finding about the gene and the disease.
PHACTR2-AS1 shares sentences with these, for which no sentence is quoted: gastric cancer (1 paper).